MAP4 (microtubule associated protein 4)
Diseases named in the same sentence as MAP4 in open-access papers (continued):
Sharing a sentence is not in itself a finding about the gene and the disease.
ciliopathy (2 papers, 2016 to 2021). A genetic disorder of the cellular cilia or the cilia anchoring structures, the basal bodies, or of ciliary function. "Impaired IFT54 function led to overexpression of the microtubule associated protein MAP4 and lowering MAP4 expression rescued polarity defects in vitro and partially rescued ciliopathy phenotypes in zebrafish morphants." (PMID 34055783, 2021).
diabetes (2 papers, 2022 to 2023). "Given that retinopathy is an important microvascular complication of diabetes, concurrent with DN, we further investigated retinopathy in MAP4 KI mice." (PMID 35902952, 2022). "To identify the variations of MAP4 and its phosphorylation in patients with clinically diagnosed diabetes, we measured them through ELISA after urine of diabetic patients was collected." (PMID 35902952, 2022). "Simultaneous occurrence of retinopathy in MAP4 KI mice suggested the nephropathy may attribute to the onset of microvascular disease in diabetes." (PMID 35902952, 2022). "The diabetic retinopathy and DN are the main microvascular complications of diabetes, and the co-occurrence of retinopathy and nephropathy in MAP4 KI mice suggest that the MAP4 phosphorylation may act as the common mechanism mediating the microvascular disease in diabetes." (PMID 35902952, 2022).
ischemia (2 papers, 2020 to 2025). A hypoperfusion of the BLOOD through an organ or tissue caused by a PATHOLOGIC CONSTRICTION or obstruction of its BLOOD VESSELS, or an absence of BLOOD CIRCULATION. "Recently, we demonstrated an increase in the amount of both MAP4 and phosphorylated MAP4 by microtubule affinity-regulated kinase 4 (MARK4) in mouse cardiomyocytes after ischemia." (PMID 40678799, 2025). "Many of them have been previously correlated with response to ischemia (MAP 4, HPX, S100A proteins) as well as with angiogenic- and revascularization-related processes (LCN2, LRG1, CD44, MAPKAPK2)." (PMID 32143690, 2020).
leukemia (2 papers, 2014 to 2020). A malignant (clonal) hematologic disorder, involving hematopoietic stem cells and characterized by the presence of primitive or atypical myeloid or lymphoid cells in the bone marrow and the blood. "Increased MAP4 expression and altered expression of multiple MAP4 isoforms have been detected in TBA-resistant leukemia and NSCLC cells in vitro." (PMID 24995158, 2014). "An elevated level of MAP4 and resistance to vinca alkaloids have been observed in childhood acute lymphoblastic leukemia (ALL) cells, while leukemia cell lines resistant to the epothilone and hypersensitive to microtubule-destabilizing agents increased the levels of both MAP4 and βIII tubulin." (PMID 32823874, 2020).
lung carcinoma (2 papers, 2018 to 2022). "Interestingly, lung cancer cells with mutations of resistant genes, such as ABCB5, IGFBP5, MAP4, showed high proliferation treatment by drug AZD7762." (PMID 36180906, 2022). "Researchers have found that the ratio of MAP4 to stathmin mRNA was higher in lung cancer tissues than in normal lung tissues, suggesting that the ratio might be a clinically relevant biomarker for NSCLCs." (PMID 29743960, 2018).
osteosarcoma (2 papers, 2022 to 2024). A usually aggressive malignant bone-forming mesenchymal neoplasm, predominantly affecting adolescents and young adults. "The results indicated that BRINP3 functions as an oncogene within osteosarcoma through MAP4 and thus could be used as a potential biomarker for the diagnosis and treatment of osteosarcoma." (PMID 38341398, 2024). "Overall, our results revealed that BRINP3 functions as an oncogene in osteosarcoma through MAP4 and might be a potential biomarker for diagnosis and therapeutic targets for osteosarcoma." (PMID 35845140, 2022). "Next, we investigated whether upregulated MAP4 was involved in BRINP3-induced osteosarcoma progression in vitro." (PMID 35845140, 2022). "BRINP3 downregulation might suppress the proliferation and invasion of osteosarcoma cells by inhibiting the expression of MAP4." (PMID 35845140, 2022). "Thus, our results demonstrated that BRINP3 promotes osteosarcoma progression possibly through the activation of MAP4." (PMID 35845140, 2022). "It promoted osteosarcoma proliferation and invasion through MAP4 in vitro." (PMID 35845140, 2022). "Interacting in vitro with MAP4 (microtubule-associated protein 4) at the protein level, BRINP3 might promote the proliferation and invasion of osteosarcoma cells by upregulating MAP4 expression." (PMID 35845140, 2022). "Overall, our results demonstrate that BRINP3 functions as an oncogene within osteosarcoma through MAP4 and could therefore be used as a potential biomarker for osteosarcoma diagnostics and therapeutics." (PMID 35845140, 2022). "Similarly, we found that BRINP3 could stimulate the proliferation and invasion of osteosarcoma by upregulating MAP4, suggesting that MAP4 might be related to the malignant progression of osteosarcoma." (PMID 35845140, 2022). "MAP4 could resist the inhibitory effect of downregulation of BRINP3 on the proliferation and invasion of osteosarcoma cells, suggesting that BRINP3 regulates the malignant progression of osteosarcoma cells at least partly through MAP4." (PMID 35845140, 2022).
acute T-cells leukemia (1 paper, 2016). "A negative effect of MAP4 on mitosis was previously reported: when transiently induced in human K562 erythroleukemia cells, DG75 Burkitt's lymphoma cells or Jurkat acute T-cells leukemia, MAP4 induced mitotic arrest with the presence of monopolar spindles." (PMID 26822478, 2016).
amnestic disorder (1 paper, 2023). Systematic and extensive loss of memory caused by organic or psychological factors. "MAP4 was upregulated in MCI and was revealed to be associated significantly with tauopathy and amnestic disorder terms in disease alliance (FDR = 0.021)." (PMID 38107644, 2023). "Additionally, neurodegenerative disease and amnestic disorder were among the disease alliance enriched terms and included MAP4 and RHOA proteins (FDR = 0.042)." (PMID 38107644, 2023).
cardiomyopathy (1 paper, 2019). A disease of the heart muscle or myocardium proper. "Our previous work suggested that microtubule associated protein 4 (MAP4) phosphorylation led to mitochondrial dysfunction in MAP4 phosphorylation mutant mice with cardiomyopathy, but the detailed mechanism was still unknown." (PMID 30906793, 2019).
cortical dysplasia (1 paper, 2017). "And FSCN1, CRMP1, NDRG1, DPYSL5, MAP4, and FABP3 were selected for validation and identified to be increased in childhood cortical dysplasia patients, while PRDX6 and PSAP were identified decreased." (PMID 28222113, 2017).
dementia (1 paper, 2023). Loss of intellectual abilities interfering with an individual's social and occupational functions. "Five autoantibodies in particular, were dysregulated in dementia and MCI, including CAMK2A, CKS1B, ETS2, MAP4, and NUDT2." (PMID 38107644, 2023). "Five autoantibodies were commonly dysregulated in both dementia and MCI, including anti-CAMK2A, CKS1B, ETS2, MAP4, and NUDT2." (PMID 38107644, 2023). "Five autoantibodies (CAMK2A, CKS1B, ETS2, MAP4, and NUDT2) were dysregulated in both dementia and MCI." (PMID 38107644, 2023). "We also show that Anti-MAP4 antibodies were upregulated in patients with MCI and dementia." (PMID 38107644, 2023).
diabetic kidney disease (1 paper, 2022). Progressive kidney disorder caused by vascular damage to the glomerular capillaries, in patients with diabetes mellitus. "Thus, we observed worse diabetic nephropathy phenotype in aged MAP4 KI mice." (PMID 35902952, 2022).
Down syndrome (1 paper, 2020). "Our previous study showed that MAP4 phosphorylation is deemed a crucial factor in mediating mitochondrial apoptosis, morphological and functional disruption, and heart defects, which is partially similar to the mitochondrial phenotype of Down syndrome." (PMID 32982783, 2020). "However, whether MAP4 is involved in Down syndrome remains unclear and warrants further studies." (PMID 32982783, 2020).
esophageal cancer (1 paper, 2023). A primary or metastatic malignant neoplasm involving the esophagus. "In this study, we found ERK phosphorylation, VEGFA and MMP3 were also inhibited after MAP4 knockdown, further confirmed that MAP4 played an important role in promoting esophageal cancer." (PMID 36991467, 2023).
Hepatic fibrosis (1 paper, 2015). The presence of excessive fibrous connective tissue in the liver. "Conversely, we showed that overexpression of MAP4 results in similar epithelialization phenotypes to those observed in TRAF3IP1 mutant cells indicating that TRAF3IP1-dependent increase of MAP4 expression results in NPH, retinal degeneration and hepatic fibrosis." (PMID 26487268, 2015).
Hyperammonemia (1 paper, 2023). An increased concentration of ammonia in the blood. "Shared DAP that were increased at both 6 and 24 h of hyperammonemia included Eif4b, Map4, Arpc1b, Eif3b, S100a4, Smad4, and Hist1h2bb." (PMID 37101412, 2023).
Hyperglycemia (1 paper, 2022). An increased concentration of glucose in the blood. "In cultured podocytes, MAP4 phosphorylation was universal increased following hyperglycemia as the down-stream effector of p38/MAPK, which led to podocytes undergoing functional, morphological, and molecular changes reminiscent of apoptosis and EMT through induced cytoskeleton rearrangement." (PMID 35902952, 2022).
lymph node metastasis (1 paper, 2023). "To further confirm that FBXW7 and MAP4 have prognostic impacts on survival, we included clinicopathological parameters (sex, age, tumor differentiation, lymph node metastasis) and the expression of FBXW7 and MAP4 to perform univariate and multivariate Cox proportional hazards regression analyses." (PMID 36991467, 2023).
Lymphatic Metastasis (1 paper, 2018). Transfer of a neoplasm from its primary site to lymph nodes or to distant parts of the body by way of the lymphatic system. "Moreover, Kaplan-Meier survival curves showed that the patients with lymphatic metastasis, higher TNM stage, and elevated MAP4 expression had a significantly poorer OS." (PMID 29743960, 2018).
mucinous carcinomas (1 paper, 2019). "Syk, MAP4 and calpain-1 appeared to significantly correlate with each other in the whole cohort, with calpain-1 being more highly associated with MAP4 and Syk in mucinous carcinomas." (PMID 30737623, 2019).
myocardial infarction (1 paper, 2024). Gross necrosis of the myocardium, as a result of interruption of the blood supply to the area, as in coronary thrombosis. "Recently, Mark4 was reported to regulate cardiomyocyte contractility by promoting the phosphorylation of microtubule-associated protein 4 and acted as a promising therapeutic target for improving cardiac function after myocardial infarction." (PMID 38301049, 2024).
Nephropathy (1 paper, 2022). A nonspecific term referring to disease or damage of the kidneys. "In MAP4 KI- and STZ-induced mice, nephropathy progress overtime is the result of accumulated damage induced by MAP4 hyperphosphorylation or high glucose." (PMID 35902952, 2022). "Salient findings from current study indicated that MAP4, the classical skeletal protein, was phosphorylated in the urine of diabetic patients and the kidney of the STZ-induced diabetic mice, which was accompanied with glomerular proteinuria associated with nephropathy." (PMID 35902952, 2022).
oral squamous cell carcinomas (1 paper, 2018). "Downregulation of MAP4 is associated with poor differentiation and proliferation in primary oral squamous cell carcinomas." (PMID 29743960, 2018).
preeclampsia (1 paper, 2025). Preeclampsia is a hypertensive disorder of pregnancy that is characterized by new-onset hypertension with proteinuria presenting after 20 weeks of gestation, and depending on mild or severe forms may initially present with severe headache, visual disturbances, and hyperreflexia. "Loss of MAP4 results in the loss of PI3Kα targeting and loss of PI3K-Akt signaling downstream of multiple agonists, which was consistent with the result of this article that the EML4 was downregulated and PI3K/Akt/eNOS pathway was inhibited in the preeclampsia model group." (PMID 40717981, 2025).
renal carcinoma (1 paper, 2023). A carcinoma arising from the epithelium of the renal parenchyma or the renal pelvis. "In our study, we have highlighted the roles of CHKB-AS1 and MAP4 in modulating the PI3K/Akt/mTOR pathway and contributing to NVP-BEZ235 resistance in renal carcinoma." (PMID 38093375, 2023).
schizoaffective disorder (1 paper, 2018). "In MAP4, we observed both a missense de novo variant and an inherited pathogenic missense variant in patients with schizoaffective disorder." (PMID 29531218, 2018).
vascular dementia (1 paper, 2023). A degenerative vascular disorder affecting the brain. "MAP4, along with tau and MAP1, have been reported to be homocysteinylated with accumulation in protein aggregates in the brains of patients with AD and vascular dementia." (PMID 38107644, 2023).
viral infection (1 paper, 2012). "In this view, the cleavage of MAP4 and MAP2 has been characterized during viral infection." (PMID 22911759, 2012).
cancer (18 papers, 2017 to 2025). A tumor composed of atypical neoplastic, often pleomorphic cells that invade other tissues. "Mechanistically, ARID1A loss increases the phosphorylation level of MAP4 (microtubule-associated protein 4), which is a key microtubule dynamics regulator in cancer cells." (PMID 41360780, 2025). "Over years, MAP4 was narrowly reported to be associated with cancer progression or treating response." (PMID 38093375, 2023). "Collectively, these results strongly demonstrated that elevated MAP4 expression is associated with the increased metastatic potential of cancer cell and worse long-term survival of LADC patients." (PMID 29743960, 2018). "To date, little research has been done on the association between MAP4 and human cancer." (PMID 38341398, 2024). "MAP4 function is associated with tumour metastasis or a poor prognosis in human cancers." (PMID 38341398, 2024). "So far, there have been few research on the association between MAP4 and human cancers." (PMID 35845140, 2022). "As a key regulator of microtubule stability, MAP4 is considered as an important effector in a variety of cancers." (PMID 41360780, 2025). "Overexpression of MAP4 has been shown to sensitize cancer cells to paclitaxel by promoting microtubule stabilization, demonstrating the importance of the pre-cellular status of microtubules in determining their response to microtubule-stabilizing agents." (PMID 40075632, 2025). "An overexpression of MAP4 has been shown to increase microtubule stability, thereby enhancing the sensitivity of cancer cells to paclitaxel and other microtubule-stabilizing agents." (PMID 40075632, 2025). "In terms of prostate cancer, MAP4 has also been considered a potential biomarker for cancer detection and differentiation of prostate tumours with different malignancies and aggressiveness." (PMID 38341398, 2024). "The present study confirmed that loss of FBXW7 function effectively induced the proliferation and metastasis of cancer cells via MAP4-ERK-VEGFA." (PMID 36991467, 2023). "FBXW7 was decreased and mutated in ESCC, and elevated MAP4 increased activation of the ERK pathway, which enhanced the characteristics of cancer cells." (PMID 36991467, 2023). "In particular, genes known to be associated with cancer such as LAMC2, UBE2C, AKT2, AKT2, BOK, MAP4, and FANCD2 were noted to be aberrantly spliced, indicating that the aberrant expression of CPSF1 significantly altered the ASEs of oncogenes in each dataset." (PMID 32437477, 2020). "Both Syk and MAP4 showed granular/diffuse staining with heterogeneity between adjacent cancer cells." (PMID 30737623, 2019). "To determine the effects of MAP4 on cancer cell migration and invasion, we repressed MAP4 expression in A549 and H1299 cells using the specific MAP4-siRNA." (PMID 29743960, 2018). "In this study, we demonstrated that MAP4 is an independent prognostic factor of LADC with the ability to promote cancer cell migration and invasion." (PMID 29743960, 2018). "In the process of cancer chemotherapy, an antimicrotubule drug is administered safely at a time, and cancer cells are more sensitive to DNA-damaging agent when MAP4 is downregulated." (PMID 29743960, 2018). "Although the underlying mechanism is unclear, the evidence seems to indicate that MAP4 is an important regulator during cancer progression." (PMID 29743960, 2018). "Other drug targets for cancer therapeutics with high CAP scores include MAP4 (60%) and TUBB1 (30%), which are targets of paclitaxel, MAP1A (42%), a target of estramustine, CD3G (39%), a target of muromonab, and PARP1 (37%), a target of olaparib." (PMID 29273096, 2017). "MAP4 is a key microtubule dynamics regulator in cancer cells." (PMID 41360780, 2025). "Since EMT is a critical step in cancer invasion and metastasis, we hypothesized that radiation-induced EMT and acquired radioresistance might be associated with MAP4." (PMID 38341398, 2024).
cancer (continued). "In the blue module (associated with the untreated cancer cells), the enriched pathways were “Cilium Disassembly”, “Microtubule”, “Tubulin Binding”, “Myosin Binding”, and “Lamellipodium Assembly”, where the genes KIF1C, MAP4, ACTG1, ABLIM3, TRIOBP are involved." (PMID 38534323, 2024). "At the single nucleotide polymorphism (SNP) mutation level and transcriptional level, we found that MAP4, YWHAG, KSR2, SPAG9, and CEP250 gene-related loci are different in cancer and paracancer tissues, and MAP4, YWHAG, CEP135, and CEP250 differed significantly at the transcriptional level." (PMID 36705386, 2023). "Furthermore, in vitro studies have shown that MAP4 knockdown can effectively prevent cancer cell migration and tumor invasion during tumor development in LUAD." (PMID 34660263, 2021). "Clinical statistical analysis also showed that MAP4 protein could accelerate tumor invasion and cancer cell migration, which are closely related to the progression of LUAD and poor prognosis." (PMID 34660263, 2021). "Recently, some studies have reported a role for MAP4 in human cancers." (PMID 31040780, 2019). "Significant correlations between MAP4, Syk, and calpain-1 suggest that calpain, Syk and MAP4 might be interrelated and interact on each other to modulate cancer cell spread." (PMID 30737623, 2019). "Until now, there are still few studies of the relationship between MAP4 and human cancers." (PMID 29743960, 2018). "However, few studies have focused on the relationship of MAP4 function with cancer progression or poor prognosis in human cancer." (PMID 29743960, 2018). "The present study has some limitations, such as the small sample size and the unknown potential molecular mechanism between aberrant MAP4 expression and cancer progression in LADC." (PMID 29743960, 2018). "In this study, we demonstrated that expression of MAP4 was closely correlated with LADC progression and poor prognosis by promoting cancer cell invasion and migration." (PMID 29743960, 2018).